IL6 (interleukin 6)
Diseases named in the same sentence as IL6 in open-access papers (continued):
Sharing a sentence is not in itself a finding about the gene and the disease.
experimental autoimmune encephalomyelitis (85 papers, 2010 to 2025). An autoimmune demyelinating disease of the central nervous system that is produced experimentally in animals by the injection of homogenized brain or spinal cord in Freund's adjuvant. "IL-9 neutralization and IL-9 receptor deficiency led to a reduction in Th17 cells and IL–6-producing macrophages in the central nervous system, ultimately ameliorating the development of experimental autoimmune encephalomyelitis in mice." (PMID 37894114, 2023). "In experimental autoimmune encephalomyelitis, astrocyte-derived IL-6 present in neuroinflammatory lesions has been implicated in motor disability and disease progression." (PMID 28877735, 2017). "Moreover, animal models have shown that IL-6-deficient mice exhibit resistance to the development of experimental autoimmune encephalomyelitis (EAE) symptoms." (PMID 37535585, 2023). "A study showed that B cells could secret an abundance of IL-6 and exhibited pathogenic effects in experimental autoimmune encephalomyelitis, an animal model for MS." (PMID 28360886, 2017). "Importantly, IL-6-deficient mice have been shown to be resistant to experimental autoimmune encephalomyelitis (EAE) and display impaired macrophage activation in models of brain injury." (PMID 27681882, 2016). "IL-6 and IL-12 deficient mice fail to respond to experimental autoimmune encephalomyelitis (EAE)." (PMID 20186338, 2010). "Specifically, Tlr4-mediated NF-κB activation drives the upregulation of proinflammatory cytokines (IL6, IL1β, and TNFα), which is consistent with its role in amplifying microglial reactivity in experimental autoimmune encephalomyelitis." (PMID 40563324, 2025). "Recently, upfront IL-6 blockade mitigated irAE symptoms in a murine model of experimental autoimmune encephalomyelitis while preserving antitumor activity after anti-CTLA-4 exposure." (PMID 39403935, 2024). "IL-6 mediated the activation of immune responses in Th17 cells and Th1 cells in experimental autoimmune encephalomyelitis." (PMID 39291284, 2024). "Herein, we aimed to preclinically test the therapeutic inhibition of IL-6 signaling in experimental autoimmune encephalomyelitis (EAE) as a potential age-specific treatment for elderly MS patients." (PMID 38928437, 2024). "In a pathological example, microglia promote tissue damage in experimental autoimmune encephalomyelitis by secreting pro-inflammatory cytokines, such as TNFα, IL-6, and GM-CSF, at the peak of inflammation." (PMID 38048364, 2023). "Another high-potential possibility is the targeting of the pleiotropic cytokine IL-6, which proved to be successful in an experimental autoimmune encephalomyelitis model, and a clinical trial is also on the way." (PMID 36769093, 2023). "In conclusion, iguratimod successfully mitigated clinical signs of progressive experimental autoimmune encephalomyelitis by suppressing T helper 17 migration and inhibiting interleukin-6 production in proinflammatory-activated glial cells." (PMID 37759616, 2023). "In experimental autoimmune encephalomyelitis, miR-146a reduced Th17 differentiation by targeting IL-6 and IL-2." (PMID 35370692, 2022). "A deleterious role of IL-6 signaling in MS has been further demonstrated in studies in experimental autoimmune encephalomyelitis (EAE) mice where IL-6R blockade prevents the development of EAE in IL-6 sufficient mice and IL-6 -/- mice are resistant to EAE." (PMID 35386698, 2022). "In a study of MSC effects in experimental autoimmune encephalomyelitis, the production of IL-6 and TGF-β was also demonstrated in 2009." (PMID 34635172, 2021). "In this review article, we summarize the role of interleukin-6 (IL-6) in the pathogenesis of MS and NMOSD and the ameliorative effects of anti–IL-6 therapies in mouse models of experimental autoimmune encephalomyelitis (EAE)." (PMID 34724990, 2021).
experimental autoimmune encephalomyelitis (continued). "In the same year, it was reported that the effects of MSCs in experimental autoimmune encephalomyelitis are mediated by transforming growth factor-β and interleukin (IL)-6, and MSCT was performed in multiple sclerosis in 2012." (PMID 34635172, 2021). "Confirming the previous reports, we report that IVIG exerts anti-inflammatory effects on innate cells as shown by the inhibitory effects on IL-6 and nitric oxide production and confers protection in experimental autoimmune encephalomyelitis (EAE) model." (PMID 26796539, 2016). "For instance, complement C5a has been shown to promote Th17-mediated autoimmune arthritis in SKG mice and experimental autoimmune encephalomyelitis by inducing IL-6 from antigen-presenting cells." (PMID 23285141, 2012). "Treatment with recombinant HSPB1 has shown translational potential, reducing the paralytic symptoms when injected intraperitoneally in the experimental autoimmune encephalomyelitis mouse model, alongside decreased levels of the inflammatory cytokines IL-2, IL-6, and IFNγ." (PMID 38507480, 2024). "Furthermore, the deletion of dendritic cell MST1 has been shown to increase IL6 expression, leading to the promotion of Th17 differentiation and worsening experimental autoimmune encephalomyelitis." (PMID 39700261, 2024). "Indeed, it has been demonstrated that B cell-derived IL-6 plays an important role in experimental autoimmune encephalomyelitis (EAE) and MS." (PMID 36010934, 2022). "Moreover, a prior study indicated that down-regulation of Arid5a led to diminished levels of IL-6 in LPS-treated mice, and further prevented development of experimental autoimmune encephalomyelitis." (PMID 35725649, 2022). "Hence, it has been reported that in VPAC2-deficient mice with experimental autoimmune encephalomyelitis, proinflammatory cytokines (TNF-α, IL-6, IFN-γ (Th1), and IL-17 (Th17)) increased, and anti-inflammatory cytokines (IL-10, TGF-β, and IL-4 (Th2)) decreased." (PMID 36101343, 2022). "Moreover, Nrf2 suppresses lipopolysaccharide-mediated macrophage inflammatory response by blocking IL-6 and IL-1β transcription, in Experimental autoimmune encephalomyelitis (EAE) mouse models." (PMID 32380663, 2020). "Interleukin-6 (IL-6) is a pleiotropic cytokine that controls numerous physiological processes both in basal and neuroinflammatory conditions, including the inflammatory response to experimental autoimmune encephalomyelitis (EAE)." (PMID 33059703, 2020). "In addition, lnc-MALAT1 expression is decreased in the spinal cords of mice with experimental autoimmune encephalomyelitis, and its knockdown raises the level of inflammatory cytokines (including IL-1 and IL-6)." (PMID 33111743, 2020). "Inhibiting dendritic cell–derived IL-6 production could suppress Th17 differentiation in experimental autoimmune encephalomyelitis and experimental autoimmune myocarditis." (PMID 33643041, 2020). "CD4+ T cells activated either in the presence of IL-6 and TGF-β, or IL-6, IL-1 and IL-23 both produce IL-17, but those skewed with TGF-β appear to be less inflammatory and fail to transfer susceptibility to experimental autoimmune encephalomyelitis (EAE)." (PMID 24475259, 2014). "Interestingly, the IL-6+ B cells in all four genotypes were CD21lo/−, which is the same phenotype as the B cells that are the major source of IL-6 in mice with experimental autoimmune encephalomyelitis." (PMID 24637841, 2014). "In MS, inflammatory activity of autoreactive Teff has mainly been attributed to impaired Treg function whereas in EAE (experimental autoimmune encephalomyelitis, the corresponding mouse model of MS) a pivotal role of IL-6 in disease development and maintenance was suggested." (PMID 24155968, 2013). "Moreover, in the same study, exogenous ghrelin suppressed spinal cord levels of TNF-α, IL-1β and IL-6 mRNA in a mouse model of experimental autoimmune encephalomyelitis (EAE)." (PMID 23509933, 2013).
experimental autoimmune encephalomyelitis (continued). "Additionally, IL-25 may suppress Th17 cell responses through downregulation of IL-23, IL-1β, and IL-6 expression in activated dendritic cells which may protect mice from severe experimental autoimmune encephalomyelitis." (PMID 34956328, 2021). "A study in a model of experimental autoimmune encephalomyelitis in mice found that Hypericum perforatum extract in combination with gold nanoparticles decreased levels of IFN-γ, IL-17A and IL-6 and increased those of TGF-β, IL-10 and IL-4." (PMID 37687297, 2023). "In experimental autoimmune encephalomyelitis (EAE), GA positively regulates inflammation by increasing anti-inflammatory IL-4, IL-10 and IL-13, while the pro-inflammatory cytokines IL-6, IL-12 and TNF-α are reduced." (PMID 36831209, 2023). "LH2171 injection also inhibited development of experimental autoimmune encephalomyelitis (EAE) and IL-6 expression in inguinal lymph nodes in mice immunized with a peptide containing amino acid sequence (139–151 residues) of the proteolipid protein." (PMID 31057558, 2019). "In mice with experimental autoimmune encephalomyelitis, myelin-specific Tregs were detected in the brain and spinal cord, but their function was inhibited by TNF and IL-6; these two cytokines are expressed in the rJ2.2-infected CNS." (PMID 25102154, 2014). "Naïve T cells activated in the presence of IL-6 and TGF-β differentiate to Th17 cells to drive experimental autoimmune encephalomyelitis (EAE) and collagen-induced arthritis, both of which are alleviated in IL-6−/− mice." (PMID 24185641, 2014). "They showed that ESA decreased the peak clinical severity of experimental autoimmune encephalomyelitis in a dose-dependent manner, with a simultaneous marked decrease of TNF and the pro-inflammatory cytokine IL-6 in the spinal cord." (PMID 22583484, 2012). "In experimental autoimmune encephalomyelitis, BBG-dependent P2 × 7R antagonism resulted in decreased BBB damage with normalized levels of PDGFβR and claudin-5 and pro-inflammatory cytokines, IL-1β, IL-6, and TNF-α." (PMID 39342243, 2024). "These mice also exhibited worsened experimental autoimmune encephalomyelitis (EAE), with infiltration of neutrophils, B-cells and Th1 cells into the brain, along with demyelination and increased levels of IFN-γ, IL-6 and IL-17, ultimately resulting in earlier lethality." (PMID 36969252, 2023). "In the mouse, IL-6 mainly induce the differentiation of naive CD4-positive T cells into Th17 cells, whereas anti-IL-6 therapy effectively suppresses the onset of experimental autoimmune encephalomyelitis via the inhibition of the development of autoantigen-specific Th17 cells." (PMID 36389702, 2022). "Several studies have shown increased levels of the cytokines TNF-α, IL-1β, and IL-6 in the DRG of animals with chronic pain induced by chemotherapeutic paclitaxel, chronic constriction of the sciatic nerve, experimental autoimmune encephalomyelitis, operation, or inflammation." (PMID 33355900, 2021). "Also, in experimental autoimmune encephalomyelitis (EAE), MZ B cells and Transitional B cells act as a source of both IL-6 and IL-10 cytokines." (PMID 34209841, 2021). "Due to its ability to bind to these regions, the novel function of Arid5a in mRNA stability was first identified when it was found to bind to the Il-6 3′UTR in the cytoplasm, promoting the production of IL-6 in vivo and inducing experimental autoimmune encephalomyelitis (EAE)." (PMID 31867000, 2019). "In line with our findings, CD200Fc treatment significantly decreased the production of TNF and IL-6 but not of IL-10 or TGF-β in microglial cells of mice with experimental autoimmune encephalomyelitis." (PMID 26891688, 2016). "In addition, our preliminary experiments in a rat model of experimental autoimmune encephalomyelitis (EAE) suggested that the application of both GM-CSF/IL-6- and GM-CSF/IL-6/PGE2-induced bone-marrow cells can suppress the development of EAE symptoms, and the duration of the disease." (PMID 30936876, 2019).
neuropathy (84 papers, 2007 to 2025). A disorder affecting the nervous system that manifests with pain, tingling, numbness, and/or muscle weakness. "Recently, high IL-6, lower serum albumin, more severe neuropathy and ascites were identified as factors associated with development of calciphylaxis in POEMS patients." (PMID 38435320, 2024). "SASP factor IL-6 secreted by PQ-induced senescent human astrocytes is considered to be a crucial cytokine that causes neuropathy." (PMID 38762455, 2024). "We demonstrate that adult C57BL/6 mice deficient in IL-6 are protected from developing functional and histological changes of paclitaxel-induced neuropathy." (PMID 31969555, 2020). "Among POEMS patients, higher disease activity, including more severe neuropathy and ascites, higher serum levels of interleukin-6, and lower serum albumin levels, was associated with the development of calciphylaxis." (PMID 27068711, 2016). "Elevated levels of both IL-6 and IL-10 were associated with reduced neuropathy in experimental animals." (PMID 26090964, 2015). "Due to its importance in controlling innate immunity and inflammation, IL-6 is generally accepted to contribute to pain and hypersensitivity associated with inflammation, neuropathy or cancer." (PMID 21951917, 2011). "The importance of these studies in the public health of the population is great, since in addition to periodontal involvement, a higher prevalence of neuropathies related to a greater increase in IgA or cardiovascular risk systematically associated with IL-6 and CPR have been recorded." (PMID 40141192, 2025). "For instance, sustained IL-6 not only wastes muscle via Stat3, but might also hinder the regrowth of nerve terminals (chronic IL-6 can cause neuropathy in some contexts) and impair the differentiation of muscle stem cells." (PMID 40869331, 2025). "Interleukin‐6 (IL‐6) could be a target of future research with regards to VTE risk in patients with anti‐MAG neuropathy, as they have higher median IL‐6 levels than healthy controls." (PMID 38015467, 2024). "Interestingly, bortezomib-induced neuropathy is associated with relative increases in the number of Th2 cells and IL-6 levels." (PMID 27088023, 2016). "A separate preclinical study demonstrated that concurrent administration of interleukin-6 and cisplatin, vincristine, or paclitaxel in rodents prevented electrophysical abnormalities associated with neuropathy as well as pathological changes in peripheral nerves." (PMID 25596818, 2015). "Similarly, in this study both IL-6 and IL-10 were inversely associated with neurological signs of tremor and neuropathy." (PMID 26090964, 2015). "The results of animal experiments indicated that elevated serum TNFα expression in DPN rats and elevated sciatic nerve IL-6 and IL-1β levels in diabetic rats were associated with neuropathy, this suggests that inflammatory factors may play a role in the pathogenesis of neuropathy." (PMID 39193373, 2024). "MO-administered neuropathy models of rats also showed reduced levels of serum IL-6, IL-1β, and TNF-α and reduced oxidative stress." (PMID 40297338, 2025). "Our patient had evidence of cytokine dysregulation, including high VEGF and IL-6, neuropathy, low albumin, and severe ascites." (PMID 38435320, 2024). "Modulating inflammatory pathways, particularly IL-6, presents a promising therapeutic target for managing both neuropathy and immune dysfunction." (PMID 39857603, 2024). "Liraglutide showed potential neuroprotective benefits by reducing neuroinflammatory cytokines, specifically interleukin-6 in the early stages of neuropathy." (PMID 38983905, 2024). "They found the level of IL‐6 was correlated with neuropathy in younger patients with DM for less than 10 years." (PMID 39474345, 2024). "Total calcium, tumor necrosis factor-α (TNF-α), interleukin-6 (IL-6), interleukin-10 (IL-10), myeloperoxidase, and severe neurodegeneration were also examined, as they were strongly associated with VCR-induced neuropathy in animal models." (PMID 37107178, 2023).
neuropathy (continued). "For instance, the CB2 agonist MDA7 prevented mechanical hyperalgesia and reduced the expression of TNF, IL-1β, and IL-6 in the spinal cords of mice with neuropathy induced by paclitaxel." (PMID 37891972, 2023). "Inflammatory mediators, such as TNF-α, IL-1, and IL-6, were shown in clinical and experimental research to contribute to neuropathy progression and maintenance." (PMID 37107178, 2023). "TNF-α is a pro-inflammatory cytokine whose involvement in neuropathy is more obvious than those of IL-6 or C-reactive protein." (PMID 37629665, 2023). "Until now, according to our knowledge, the majority of researchers have mostly concentrated on the classic signaling pathway-mediated effects of IL-6 in neuropathy." (PMID 36676049, 2022). "Specifically, these DEGs were associated with neuropathy-related pathways, such as GABRD, GABRP, TBX1, and SOX10, and inflammatory responses such as CXCL3, CXCL12, TNF, and IL6." (PMID 36147849, 2022). "In contrast, targeting DOR is required to modulate IL-6 increase mediated by neuropathy in the late phase, confirming a critical role of IL-6 in inducing neuropathy chronicization and maintenance." (PMID 35682543, 2022). "Interleukin-6 tended to be higher in T2D patients than healthy controls and even higher in T2D patients with painful neuropathy but lower in patients with painless DPN." (PMID 35155045, 2022). "Patients co-infected with leprosy and SARS-CoV-2 have elevated levels of IL-6 and IL-12B and develop neuropathy." (PMID 36157452, 2022). "A recent study has also found a significant decrease in the neuropathy severity, a decrease in the IL-6 level and an increase in the IL-10 level after treatment with cholecalciferol (40,000 IU/week) for 24 weeks in patients with T2DM and DPN." (PMID 33777989, 2021). "They both activate glial and immune cells to release proinflammatory cytokines such as TNF-α, IL-1β, IFN-γ, and IL-6, and chemokines such CCL2 and CCL5, which cause neuronal hyperexcitability, neurodegeneration, neuropathies including neuropathic pain." (PMID 35095888, 2021). "An RCT study of 67 patients of DM II with neuropathy and administration of Vitamin D 40,000 IU weekly revealed improvement of symptoms and decrease in interleukin-6 (IL-6) and elevation of interleukin-10 (IL-10)." (PMID 34567869, 2021). "In summary, these results demonstrate that IL-6 knockout mice are protected from PTX-induced neuropathy." (PMID 31969555, 2020). "Given the pivotal role of IL-6 in the development of PTX-induced neuropathy, we were interested which effects IL-6 mediates in vitro." (PMID 31969555, 2020). "In this study, we demonstrate an important role for IL-6 in the development of PTX-induced neuropathy." (PMID 31969555, 2020). "Next, we evaluated a preventive application of IL-6-neutralizing antibodies (IL-6-AB) in our model of PTX-induced neuropathy." (PMID 31969555, 2020). "In order to further elucidate the mechanistic role of IL-6 signaling in the pathophysiology of PTX-induced neuropathy, we aimed to investigate how PTX-induced Ca2+ dyshomeostasis and IL-6 synthesis are linked." (PMID 31969555, 2020). "Interleukins (IL-1beta, IL-18 and IL-6) are recognized as the first pronociceptive cytokines in neuropathy and are known to be strongly activated upon neural damage in the CNS and PNS." (PMID 32691345, 2020). "The correlation of serum IL-6 levels with symptoms of neuropathy, especially neuropathic pain 9 led us to investigate serum IL-6 levels before initiation and after completion of chemotherapy." (PMID 31969555, 2020). "In summary, these results demonstrate the protective effect of a preventive treatment with IL-6-neutralizing antibodies in an animal model of PTX-induced neuropathy." (PMID 31969555, 2020). "Both IL-6 and IL-10 high levels have been described to be responsible for the neuropathy decline in T. brucei." (PMID 31687034, 2019).